LINC00539 (long independently transcribed non-coding RNA 539)
Synonyms: LINC00422
Gene: Long non-coding RNA gene on chromosome 13 (21,302,829 to 21,362,139, reverse strand). Ensembl gene ENSG00000224429.
Diseases named in the same sentence as LINC00539 in open-access papers:
LINC00539 is named in the same sentence as 2 diseases in open-access papers, as found by Europe PMC text mining. Sharing a sentence is not in itself a finding about the gene and the disease. The quoted sentences say what the papers report.
myeloid leukemia (1 paper, 2025). A clonal proliferation of myeloid cells and their precursors in the bone marrow, peripheral blood, and spleen. "Third, integrative analysis identified 570 genes upregulated at both the eccDNA and mRNA levels, including myeloid leukemia drivers (FLT3, RUNX1, CD33) and oncogenes (MAP2K2/3, LINC00539), mirroring the “eccDNA–oncogene amplification” axis observed in solid tumors." (PMID 41278279, 2025).
LINC00539 also shares sentences with these, for which no sentence is quoted: tumor (1 paper).